GAGE12B (G antigen 12B)
Synonyms: OTTHUMG00000024142
Gene: Protein-coding gene on chromosome X (49,529,869 to 49,529,985, forward strand). Ensembl gene ENSG00000236737.
Diseases named in the same sentence as GAGE12B in open-access papers:
GAGE12B is named in the same sentence as 3 diseases in open-access papers, as found by Europe PMC text mining. Sharing a sentence is not in itself a finding about the gene and the disease. The quoted sentences say what the papers report.
gastric cancer (1 paper, 2019). A primary or metastatic malignant neoplasm involving the stomach. "Consistent with our findings, in a previous study, GAGE12B (also known as GAGE12D) was reported to mediate gastric cancer metastasis and growth." (PMID 30871606, 2019).
GAGE12B also shares sentences with these, for which no sentence is quoted: cancer (2 papers); tumor (1).